CXCR3 (C-X-C motif chemokine receptor 3)
Diseases named in the same sentence as CXCR3 in open-access papers (continued):
Sharing a sentence is not in itself a finding about the gene and the disease.
COVID-19 (continued). "And, spike-specific CXCR3+ TFH cells exhibited higher activation status and greater IL-21 secretion than spike-specific CXCR3− TFH cells in both COVID-19 convalescents and vaccinees upon antigen exposure." (PMID 37802996, 2023). "This study examined the relationship between levels of the chemokines CXCL9, CXCL10, CXCL11, and CXCR3 and mortality in patients with COVID-19.." (PMID 37493737, 2023). "In the peripheral blood of patients recovered from COVID-19, the proportion of CXCR3+CCR6– Tfh1 and CXCR3–CCR6– Tfh2 cells increased compared to the control, while the CXCR3–CCR6+ Tfh17 cell count was significantly reduced." (PMID 35632823, 2022). "The inhibition of the CXCL10/CXCR3 pathway reduces inflammation and cytokine storm in response to COVID-19." (PMID 35409036, 2022). "We discovered several chemokine receptor signatures on NK cells (N = 8) associated with the development of severe COVID-19, including upregulated CX3CR1 expression on early NK cells and increased levels of CCR4, CCR9 and CXCR3 on terminal NK cells." (PMID 36433939, 2022). "Together, the results indicate that the major subsets affected during moderate infection with COVID-19 or influenza are lymphocytes expressing CXCR3 as well as CXCR6 and CCR5." (PMID 35371005, 2022). "Severe COVID-19 patients that develop lung injury showed expanded KLRG1+ Tregs that express Cxcr3, Il10, Il12b1, Ilrb1, Tbx21, Gata3 gene signatures similar to what was found in this study." (PMID 35634302, 2022). "In contrast, there was a negative correlation between CXCL10 and CXCL11 levels and the percentage of CXCR3+ ILCs in COVID-19 patients." (PMID 35159352, 2022). "CXCR5 expression was altered in acute and convalescent COVID-19 subjects, whereas the frequencies of CXCR3+ and CCR4+ cells were decreased in both patient groups vs. HC." (PMID 36146713, 2022). "In the peripheral blood of influenza and COVID-19 patients, fewer CXCR3+ CD16- NK cells are present, presumably because these cells have been recruited to the lung." (PMID 35844626, 2022). "Overall, T cells displayed similar expression patterns as NK cells in terms of lower frequencies of CXCR3+ CD8+ T cells in COVID-19 patients and of CXCR3+ and CXCR6+ CD8+ T cells in influenza patients." (PMID 35371005, 2022). "In post-COVID-19 patients, we observed co-upregulation of groups of related red module proteins such as the CXCR3 chemokines (CXCL9, CXCL10, and CXCL11), and interleukin-1A (IL1A) and its antagonist IL1RN." (PMID 35151371, 2022). "Frequencies of NK cells and T cells expressing CXCR3, CXCR6, and CCR5 were altered in peripheral blood of COVID-19 and influenza patients, in line with increased transcript expression of CXCR3, CXCR6, and CCR5 and their respective ligands in BAL fluid." (PMID 35371005, 2022). "CD4+ T cells primed in the setting of severe COVID-19 also appeared to have impaired Th1 memory formation, based upon decreased percentages of circulating CXCR3+CCR4– cells at early memory time points." (PMID 35857584, 2022). "CXCR3-expressing T cells are important in antiviral immune responses and reported to be higher in the blood of severe COVID-19 patients." (PMID 36526890, 2022). "Increasing the CXCR3+CCR6− CD8+ T cell (Tc1) level was noted in adenoid tissue from convalescent COVID-19 patients compared to control subjects." (PMID 36146713, 2022). "Our data indicate a universal role for CXCR3-mediated lung-homing of NK cells and T cells in COVID-19 and influenza and an additional role for recruitment via CXCR6 and CCR5 in CD8+ T cells." (PMID 35371005, 2022). "Second, we identified shared expression of CXCR3 in multiple cell subsets that were enriched during COVID-19 convalescence." (PMID 34113347, 2021). "Surviving patients with COVID-19 had increased levels of PD-L1+CXCR3+CD8+ Teffs and CXCR5+HLA-DR+CD8+ Tscms." (PMID 34283810, 2021).
COVID-19 (continued). "Fifth, there was no statistical difference in the total CD11b+CD14+ monocytes between convalescent COVID-19 and HD, but a specific CXCR3+ CD11b+CD14+ monocyte subset was significantly increased during disease convalescence." (PMID 34113347, 2021). "During acute COVID-19 CXCR3+CCR6− Tfh1-like cells were decreased and the levels of CXCR3−CCR6+ Tfh17-like were increased then in HC and convalescent patients." (PMID 35723393, 2021). "Unsupervised analysis of MAIT cell flow cytometry phenotypes in all Atlas cohort patients and controls (n = 38) revealed a pattern of enhanced CD69 expression and diminished CXCR3 expression in both AM and AS COVID-19 patients." (PMID 32989174, 2020). "NFKB1, NFKB2, IRF1, and CXCR3 were specifically up-regulated in COVID-19, and CXCL10, STAT1, TLR4, and genes for class II HLA and immunoproteasome subunits were specifically up-regulated in influenza." (PMID 32651212, 2020). "In addition, we found that the expression level of CXCR3 in severe COVID-19 patients is higher than that in other COVID-19 patients." (PMID 40114921, 2025). "However, we observed an enhanced interaction between PF4 from CD14+ monocytes and CXCR3 from HLA_DR+ Tregs in COVID-19 patients, suggesting that PF4-CXCR3 plays an important role in maintaining homeostasis and suppressive function of Tregs." (PMID 40114921, 2025). "In addition, the expression level of CXCR3 of Tregs was significantly higher in severe COVID-19 patients than in the healthy controls in the bulk RNA-seq of Tregs." (PMID 40114921, 2025). "Notably, the heightened suppressive function of HLA_DR+ Tregs in severe COVID-19 patients, with interactions between PF4 and CXCR3, contributed to the homeostasis of HLA_DR+ Tregs in severe COVID-19 patients." (PMID 40114921, 2025). "However, under inflammatory conditions, such as colitis and Crohn’s disease, and infections, like COVID-19, the production of mainly CXCL10 strongly increases, which is associated with high tissue infiltration of activated CXCR3+ T cells." (PMID 39867906, 2024). "Additionally, it was noted that patients with severe COVID-19 had increased levels of CXCR3 on Tregs cells, indicating the upregulated capacities of Tregs to migrate to the sites of inflammation." (PMID 39519310, 2024). "Our data suggest that therapeutic targeting of immune cell recruitment via the CXCL9– CXCL10–CXCL11/CXCR3 axis may be a valuable therapeutic strategy for resolution of inflammation in severe COVID-19, where it has become uncoupled from viral clearance." (PMID 36472908, 2023). "Additionally, COVID-19 survivors with upregulated C-X-C Motif Chemokine Receptor 3 (CXCR3) also exhibited prolonged epithelial and extracellular matrix damage." (PMID 39872302, 2023). "These intercellular interaction analyses computationally infer the possibility that dysfunction of ncMono and the consequently reduced interaction of CXCL10/CXCR3 might be one of the factors responsible for driving COVID-19 severity." (PMID 37095364, 2023). "CXCR3+ Tfh cells also positively correlated with neutralizing antibody titers proposing a propable key role of CXCR3+ Tfh cells in the early production of neutralizing antibody titer in patients recovering from COVID-19." (PMID 35286241, 2022). "It was reported that the proportion of CXCR3– Tfh cells and a cytotoxic Tfh subpopulation negatively correlated with the anti-SARS-CoV-2 antibodies in COVID-19 patients, possibly because the Tfh response skewed to CXCR3+ subset, which contributes to anti-SARS-CoV-2 antibody production." (PMID 36447270, 2022). "Similarly, COVID-19 convalescents also exhibited low levels of CXCR3+ cells within ‘naïve’, CM, EM, and TEMRA CD8+ T cells." (PMID 36146713, 2022). "Indeed, our analysis of RNA-seq data from BAL fluid of COVID-19 patients suggest a CXCR3- and CXCR6-mediated recruitment of NK cells and T cells, as well as a CCR5-mediated recruitment particularly of CD8+ T cells in moderate disease." (PMID 35371005, 2022).
COVID-19 (continued). "So, knowing that CXCL10 through CXCR3 is associated with inflammatory diseases, it has been suggested that the CXCL10–CXCR3 axis may be probably involved in development of COVID-19." (PMID 35409036, 2022). "Interestingly, we revealed dramatically decreased CXCR3 expression in all CD8+ T cell maturation subsets from patients with acute COVID-19 vs. COVID-19 convalescents and healthy controls." (PMID 36146713, 2022). "Loss of CXCR3 was observed in all non-naïve T cells in COVID-19 patients, being significant in non-naïve CD8+ T cells as compared to healthy controls." (PMID 35371005, 2022). "Collectively, these preliminary data suggest that the CXCL10/CXCR3 axis may participate in CD16Int neutrophil recruitment into the lungs of patients with COVID-19." (PMID 33986193, 2021). "The data reported by others suggest that peripheral blood of patients recovered after COVID-19 had elevated proportion of CXCR3+CCR6− Tfh1 and CXCR3−CCR6− Tfh2 cells compared with control group, whereas percentage of CXCR3−CCR6+ Tfh17 cells was significantly decreased." (PMID 35723393, 2021). "Interestingly, a similar observation was made in the BAL from patients with COVID-19, where most BAL infiltrates expressed CXCR3 and/or CXCR4, and the increased presence of activated lung-homing CXCR4+ T cells was associated with fatal COVID-19." (PMID 34803691, 2021). "Our overall analysis of such Tfh cell subsets patients with acute COVID-19 indicated that CXCR3+CCR6− Tfh1-like cells were significantly decreased compared with healthy control and COVID-19 convalescent patients 3.74 ± 0.21% vs. 5.79 ± 0.27% (p < 0.001) and 5.09 ± 0.23% (p < 0.001), respectively." (PMID 35723393, 2021). "Though the mechanism has yet to be elucidated, CXCR3 ligand-producing cells are increased in COVID-19 patient’s lungs, which may indicate a CXCR3-dependent mechanism for NK cells recruitment to the lung as described in influenza A infection." (PMID 34192268, 2020). "This may contribute to elevated lung infiltration of CXCR3+ lymphocytes in COVID-19 patients." (PMID 35371005, 2022). "Additionally, increased frequencies of virus-specific cTfh cells (CD4+CXCR5+OX40+CD40L+) were observed in acute and convalescent COVID-19 cases, and the frequencies of both SARS-CoV-2-specific cTfh cells and S-specific CCR6+CXCR3-cTfh17 cells were closely associated with low disease severity." (PMID 34603308, 2021). "Furthermore, using chemokine receptors as correlates of T helper subsets, we found that the frequency of Th1 equivalents (CCR6+CXCR3+) was unaltered between healthy controls, moderate and severe COVID-19 patients, but it was increased compared to convalescent individuals." (PMID 34745145, 2021). "Furthermore, the ratio of CXCR3+ to T-box protein expression in T cell (T-bet)+ (CXCR3+/T-bet+ ratio) in CD8+ cells may be used as a predictor of severe COVID-19." (PMID 34471088, 2021). "We found that similar to monocytes CCR2 and CXCR3 were upregulated in DC3 of COVID-19 patients suggesting that DC3 together with monocytes may be recruited from the circulation to the infected lung in response to a gradient of CCL2 and CXCR3 ligands CXCL9/10/11." (PMID 34614036, 2021). "Moreover, owing to the rapid decrease in the frequency of T-box protein expression in T cell (T-bet)+ cells in both PBMCs and CD8+ cells in old RMs after SARS-CoV-2 infection, the CXCR3+/T-bet+ ratio in CD8+ cells exhibits good potential for predicting the severity of COVID-19." (PMID 34471088, 2021). "Collectively, the ligand-receptor pair of PF4_CXCR3, in the interaction between CD14+ monocyte and HLA_DR+ Tregs, facilitates the suppression of HLA_DR+ Tregs in severe COVID-19 patients." (PMID 40114921, 2025). "Although some studies have reported even more long-term immune perturbations in patients following COVID-19 recovery, these alterations are generally infection-related signatures, such as CD38+HLA-DR+ T cells and CXCR3 expression." (PMID 38429462, 2024).
COVID-19 (continued). "Especially within the lung, the main target organ for COVID-19, we detected significantly increased titers of activated CD4+ T cells, as shown for CXCR3+ cells." (PMID 38250865, 2024). "Coculture of CXCR3+ TFH or CXCR3− TFH cells with autologous memory B cells from COVID-19 convalescents and vaccinees showed that CXCR3+ TFH cells were more able than CXCR3− TFH cells to support spike-specific memory B cell differentiation into ASCs." (PMID 37802996, 2023). "They observed that dexamethasone has a specific therapeutic effect on COVID-19 by regulating the CXCL10 and CXCR3 axis." (PMID 35409036, 2022). "Vδ2Vγ9T cell clusters 20 and 25 from CR2 panel were expanded in severe and critical COVID-19 (Bonferroni-adjusted P-value range 0.00564–6.39 × 10−8) and characterized by CCR9, CXCR3 and TIGIT expression." (PMID 36433939, 2022). "Th1 and Th17 are often characterized by CXCR3 and CCR6, respectively, and CXCR3+ and CCR6+ SARS-CoV-2-specific CD4+ T cells were both detected during acute COVID-19." (PMID 35992306, 2022). "In our study, individuals recovered from severe COVID-19 had increased expression of lung-homing chemokine receptors CCR4, CXCR3 and CX3CR1 on NK cell subsets." (PMID 36433939, 2022). "Cytokine-secreting immune cells, such as CXCR3+CD4+ T cells, CXCR3+CD8+ T cells, and CXCR3+ NK cells, were shown to be elevated in severe COVID-19 patients." (PMID 35062368, 2022). "Our results suggest that autoantibodies targeting CXCR3 and AGTR1 are the most important predictors of COVID-19 severity." (PMID 35264564, 2022). "In this context, autoantibodies such as ACE2-aab, AGTR2-aab, BDKRB1-aab, CXCR3-aab, MAS1-aab, CHRM5-aab, NRP1-aab, F2R-aab, STAB1-aab appeared to play a major role in stratifying COVID-19 by disease burden." (PMID 35264564, 2022). "Further, chemokine and cytokine receptors (CXCR3, CXCR4, CXCR5, CCR4, CCR5, and CCR7) expression was increased in active COVID-19 and recovered patients." (PMID 36532041, 2022). "Four Phenograph MAIT cell clusters were found to be overrepresented in patients who died of COVID-19 and these clusters were all characterised by high CD69 expression and low/very low levels of CXCR3." (PMID 34050887, 2022). "There is a reduction in the percentage of ILCs, MAIT, NKT expressing CXCR3+ (and an increase in CCR4+), but it is expressed in γδ T cells in both moderate and severe COVID-19 patients." (PMID 35159352, 2022). "On the other hand, the levels of memory CD8+CXCR3+CCR6+ and CD45RO+CXCR3−CCR6+CD8+ T cell subsets were elevated in mild vs. moderate-to-severe COVID-19 patients." (PMID 36146713, 2022). "Here, we compared changes in NK cell and T cell subset compositions, focusing on expression of the lung-homing receptors CXCR3, CXCR6, CCR2, and CCR5, in the peripheral blood from patients with clinically moderate COVID-19 or influenza." (PMID 35371005, 2022). "Dissecting the Th cell phenotypes, we observed an apparent lower CXCR3+Th1 subset, along with higher CCR3+Th2 and CCR5+Treg frequencies, in our COVID-19 cohort." (PMID 33808906, 2021). "Circulating Th and Tfh-like cells expressing CXCR3 (Th1, Tfh1) and/or CCR6 (Th1/17, Tfh1/17 and Th17, Tfh17) showed a trend towards increased activation in patients with active COVID-19." (PMID 34614036, 2021). "CXCR3, which mediates chemotaxis in response to IFN-induced inflammatory chemokines (CXCL9, CXCL10, CXCL11), was also upregulated in COVID-19 patients’ DC3, cDC2 and monocyte subsets but downregulated in cDC1, tDC, and pDC." (PMID 34614036, 2021). "During acute COVID-19, B cells showed a reduced expression of CXCR3, CXCR5 and integrin β7 according to disease severity, with CXCR3 and CXCR5 level normalization in convalescent subjects." (PMID 34595175, 2021). "Conversely, CXCR3, ligands for which were up-regulated in BAL of COVID-19 patients, is expressed at low levels by mature CD57+ CD56dim NK cells." (PMID 32826343, 2020).
COVID-19 (continued). "If translated to the more complex human setting, these preclinical results would not support targeting CXCL10/CXCR3 axis in severe COVID-19." (PMID 39803542, 2024). "Together, these findings demonstrate that spike-specific CXCR3+ and CXCR3− TFH cells exhibit distinct kinetics, and that spike-specific CXCR3+ TFH cell responses may persist for more than 2 years in COVID-19 convalescents." (PMID 37802996, 2023). "Nonproliferating CXCR3+ cells (Th1) were reduced in COVID-19 patients, potentially as they had shifted to the Ki67+Th1 group." (PMID 36669118, 2023). "Intriguingly, the amount of IL-21 secreted by CXCR3+ TFH cells was significantly higher than that secreted by CXCR3− TFH cells from both COVID-19 convalescents and vaccinees, but not from healthy controls, upon peptide stimulation." (PMID 37802996, 2023). "Moreover, CXCR3+CCR6- Tc1 cells were decreased in patients with acute COVID-19 and COVID-19 convalescents, whereas Tc2 and Tc17 levels were increased compared to HC." (PMID 36146713, 2022). "Follow-up analysis indicated that CXCR3-aab, AGTR1-aab, MAS1-aab, CHRM5-aab, and BDKRB1-aab were the five most significant predictors of COVID-19 disease-severity classification based on the number of nodes and the Gini decrease criteria for measuring variable importance." (PMID 35264564, 2022). "Together, our results indicate a role for CXCR3+, CXCR6+, and/or CCR5+ NK cells and T cells that potentially migrate to the lungs in moderate COVID-19 and influenza patients, identifying common targets for future therapeutic interventions in respiratory viral infections." (PMID 35371005, 2022). "A report suggested that MAIT cells also expressed CXCR3, several studies have shown an increase in expression of early activation marker CD69 on MAIT cells and a decrease in expression of the homing marker CXCR3 in mild and severe cases of COVID-19." (PMID 36034704, 2022). "Moreover, in patients with COVID-19, the majority of SARS-CoV-2-specific Tfh cells had Tfh17 CCR6+CXCR3– phenotype." (PMID 36012146, 2022). "Monocytes producing ligands for CXCR3 have been shown to be expanded in the lungs of COVID-19 patients, and although not significant, CXCL10 mRNA expression was increased in monocytic macrophages from BAL fluid from COVID-19 patients with moderate disease." (PMID 35371005, 2022). "Together, these results demonstrate common activation patterns between NK cell subsets in COVID-19 and influenza patients, with a stronger activation of NK cells expressing CXCR3, CXCR6, CCR2, and/or CCR5 than NK cells lacking any lung-homing receptors." (PMID 35371005, 2022). "In both mild and severe cases of COVID-19, increased expression of the early activation marker CD69 on MAIT cells and diminished expression of the homing receptor chemokine C-X-C motif receptor 3 (CXCR3) has been reported." (PMID 34050887, 2022). "In clinical studies, convalescent individuals who experienced severe COVID-19 showed a higher induction of CXCR3+ Tfh cells when compared with those non-severe COVID-19-convalescent individuals." (PMID 36505489, 2022). "Meanwhile, they reported lower expression of CXCR3+ in total Tfh cells of both severe and non-severe COVID-19-convalescent individuals compared with the healthy controls." (PMID 35286241, 2022). "Interestingly AABs to the vaso- and immunoregulatory receptors CXCR3, CHRM5, BDKRB1, MAS1, AGTR1, F2R/PAR-1, and STAB1 were the most significant classifiers of acute COVID-19 severity in our recent study." (PMID 36238301, 2022). "In addition to displaying correlations with immune cell frequencies in the airways, the chemokines CXCL9, CXCL10, and CXCL11, and their receptor, CXCR3, are all members of the red WGCNA module that characterized the post-COVID-19 airway." (PMID 35151371, 2022). "CD4+ and CD8+ T cells in acute COVID-19 patients showed a substantial reduction of CXCR3 and CXCR5 expression, irrespective of disease severity, that is recovered upon convalescence." (PMID 34595175, 2021).